LEP (leptin)
Diseases named in the same sentence as LEP in open-access papers (continued):
Sharing a sentence is not in itself a finding about the gene and the disease.
diabetes (continued). "However, the LEP G2548A gene polymorphism among Malaysian diabetes patients has not been investigated yet." (PMID 36381191, 2022). "In addition to leptin/adiponectin, which had been widely proposed to be a sensitive indicator for evaluating diabetes risk, the ratios of HMW/total adiponectin, HOMA/adiponectin and adiponectin/ferritin were also applied for assessing diabetes." (PMID 34096884, 2021). "Therefore, the relationship between diabetes and leptin could be based on inflammatory processes that exist during DM." (PMID 34177788, 2021). "Therefore, 1 mg V/day showed no changes in the alterations caused by diabetes concerning glycemia or leptin level." (PMID 33920401, 2021). "Some results have shown that leptin may be used for diabetes and hypertriglyceridemia." (PMID 35027962, 2021). "Interestingly histamine is known to ameliorate leptin-resistance which occurs in diabetes." (PMID 32349282, 2020). "Interestingly, Db/Db mice did not develop any signs of IVD degeneration and IVDs instead appeared less mature with large notochordal cells populating the NP, suggesting that diabetes and impaired leptin signaling had more substantial effects on vertebrae than on IVDs." (PMID 32374776, 2020). "This leptin resistance at the pancreatic β cell level may contribute to dysregulation of the adipo-insular axis and accelerate the development of hyperinsulinemia and can manifest as diabetes mellitus in overweight patients." (PMID 33167521, 2020). "Dispersive effects on core diabetic traits like leptin production might help explain heterogenous presentation, progression and response to treatment; of the nearly 400 million sufferers of diabetes mellitus, many incipient affecteds are unaware of their condition." (PMID 31661517, 2019). "In addition, genes linked to human T2DM form genome wide association studies (GWAS) of human diabetes do not include genes of leptin and leptin receptor (Wang, Chandrasekera & Pippin, 2014)." (PMID 29682407, 2018). "We have confirmed in our group of normoglycemic women with no family history of diabetes that plasma leptin levels were positively associated with BMI and negatively with insulin sensitivity indexes, whereas the opposite was found both for adiponectin and HMWA." (PMID 28626772, 2017). "As it has been reported that a leptin/adiponectin imbalance plays a particular role in the development of metabolic syndrome and diabetes, both findings are of relevance and may add to the more classical cardiovascular risk factors present in the preterm study cohort." (PMID 27959909, 2016). "When entering major known cardiovascular risk factors to the Cox regression leptin levels were positively related to ischemic heart disease in men, independently of age, HbA1c, BMI, systolic blood pressure and LDL-cholesterol/HDL-cholesterol ratio, smoking, and known duration of diabetes." (PMID 25994184, 2015). "The lack of treatment effect in leptin modulation may simply be because of the fact that induced diabetes produced such weight loss that, apart from the glibenclamide group, this overwhelmed any further subtle effects of each treatment." (PMID 26699937, 2015). "Indeed, leptin has been found to be related to endothelial dysfunction in diabetes." (PMID 25994184, 2015). "Additionally, the BTBR ob/ob mouse model is dependent on leptin deficiency, which is not a characteristic of human diabetes." (PMID 25629817, 2015). "Although physiologic leptin replacement lowers blood glucose levels only slightly, it fully normalizes elevated plasma glucagon and corticosterone levels and reverses the increased hepatic expression of gluconeogenic enzymes characteristic of rats with uncontrolled diabetes." (PMID 23579596, 2013). "Thus, without additional genetic modifications, the defected leptin signaling alone at least by this mutant allele in this genetic background is unable to cause pronounced diabetes phenotype particularly at the young age." (PMID 23304119, 2012).
diabetes (continued). "Therefore, although leptin signaling is highly crucial for understanding the etiology of the diabetes, genetic elements that place demand on insulin action in response to obese states should be a focus of research using diabetes animal models." (PMID 23304119, 2012). "In the present study, we found MyD88-deficient mice fed a HFD had increased circulating levels of insulin, leptin and cholesterol, as well as liver dysfunction (increased induction of ALT levels, increased activation of JNK and cleavage of PARP), which were linked to the onset of severe diabetes." (PMID 20824098, 2010). "The induction of diabetes led to a significant increase in the levels of serum glucose (253a ± 7.1), HOMA-IR (5.5a ± 0.069), insulin (8.8a ± 0.3), and leptin (36a ± 2.10) compared to the control group." (PMID 40184394, 2025). "The altered levels of adipokines such as adiponectin and leptin, along with pro-inflammatory markers like CRP and IL-6, underscore the complexity of diabetes etiology in this population." (PMID 41523554, 2025). "The highest percentage of children from parents with a high ISCED level was in the “low leptin/IGF-1/HbA1c” status; percentages of familial hypertension, diabetes, and dyslipidemia were lowest." (PMID 39899498, 2025). "We conducted a comparative analysis of baseline marker levels between the study and control groups, including adiponectin, leptin, IL6, TNFα, IGF1, and IGF2, while also adjusting for BMI, parity, and diabetes." (PMID 38339282, 2024). "First, an increase in leptin levels in serum (SMD 0.69; 95% CI 0.36–1.02 ng/mL) and plasma (SMD 0.46; 95% CI 0.18–0.74 ng/mL) was observed in individuals with diabetes compared to controls." (PMID 39684379, 2024). "The diabetes mellitus model itself should also be carefully selected as it has been shown that wound healing in streptozotocin-induced DM (imitating type I DM) is not as impaired as in leptin-deficient mice." (PMID 39337474, 2024). "Beneficial effects from practising a Paleolithic diet as compared to a diabetes diet on weight, waist circumference, satiety, leptin, HbA1c and glucose control in randomised controlled trial participants with type 2 diabetes could be due to lower leptin resistance." (PMID 39232748, 2024). "Thus, participants with diabetes may have higher levels of serum leptin than those without diabetes, which may explain why BMI is more significantly associated with migraine in participants with diabetes." (PMID 38243194, 2024). "Lower expression in patients with diabetes was evident for SCPEP1, S100A11, LEP, PEBP1, SHGB, and APOF." (PMID 37792298, 2023). "The salivary hormones leptin, ghrelin, and GLP-1 are either higher or lower in patients with diabetes compared to the control group." (PMID 37223639, 2023). "In db/db mice, a model of diabetes, the deletion of PTP1B was found to improve leptin resistance and reduce superoxide generation." (PMID 36978976, 2023). "The association of elevated leptin SR level with high TG and deterioration of β-cell function indicate that in some individuals, particularly non-obese, dyslipidemia might be a cause rather than a complication of diabetes." (PMID 36950695, 2023). "Leptin and soluble leptin receptor levels are increased in T1DM children and related to anthropometrics parameters, metabolic control, age of debut of diabetes, and kind of insulin therapy." (PMID 36674935, 2023). "In conclusion, the salivary hormones leptin, ghrelin, and GLP-1 are produced either higher or lower in patients with diabetes compared to the control group." (PMID 37223639, 2023). "It was proposed that the influence of COVID-19 infection was amplified by DPP4 in patients with diabetes, and through its interaction with INS, leptin, IL-6 and other proteins." (PMID 34996987, 2022). "This study firstly analyzed the relationship between leptin and resistin in T2DM according to novel subgroups, providing promising prospects for precision medicine involving leptin or resistin in diabetes." (PMID 34996484, 2022).
diabetes (continued). "Comparing healthy diabetics to those with cardiovascular complications revealed a reduction in EG-VEGF and TIMP-4 (in addition to LAP (TGF-b1), Leptin, PD-ECGF, and Serpin F1) in all patients with diabetes with CAD while TIMP-1 was significantly increased." (PMID 35109843, 2022). "Additionally, TSH was positively associated with leptin in unadjusted and adjusted models, and the FT3/FT4 ratio was positively associated with leptin in unadjusted model and in model 1 (adjusted for sex, age and current smoking), but not in model 2 (further adjusted for BMI and diabetes)." (PMID 36518251, 2022). "Serum levels of leptin and IL-1 β were found to be significantly increased, and adiponectin decreased, in T2DM patients with MCI, suggesting that higher levels of leptin and IL-1 β, as well as lower levels of adiponectin, could be diagnostic biomarkers of MCI risk in elderly diabetes patients." (PMID 35682821, 2022). "Composed of four biomarkers (leptin, soluble TWEAK, homocysteine, and proinflammatory high-density lipoprotein), age, and diabetes, the PREDICTS model has relatively high sensitivity (89%) and specificity (79%)." (PMID 33936038, 2021). "Diabetes related biomarkers: GIP, GLP-1, leptin, glucagon and inflammatory cytokines: IL-4, IL-5, IL-10, IL-12, IFN-g and TNF-α were significantly affected by HFB diet compared to HF diet." (PMID 34441468, 2021). "This study is aimed at analyzing the relationship between leptin (LEP) signaling pathway and type 2 diabetes mellitus (T2DM) and at providing support for molecular genetic research on the pathogenesis of T2DM in Chinese Han population." (PMID 34589546, 2021). "Their model utilized proinflammatory HDL (piHDL), leptin, TWEAK, homocysteine, history of diabetes, and age as predictors and had a sensitivity of 89% and specificity of 79% (AUC not available)." (PMID 33936038, 2021). "Also, it appears to have a role in diabetes mellitus (DM) and blood glucose, as leptin analog decreases plasma glucose and plasma insulin increases insulin sensitivity." (PMID 35027962, 2021). "Diabetes related biomarkers, gastric inhibitory polypeptide (GIP), leptin, glucagon, and inflammatory cytokines interleukin 4 (IL-4) and IL-5, 10 and 12, IFN-g and TNF-α were significantly affected by HFB diet." (PMID 34441468, 2021). "The presence of diabetes was better identified by the HOMA index (AUROC leptin/ghrelin ratio = 0.658, AUROC leptin = 0.632, AUROC ghrelin = 0.682, AUROC HOMA index = 0.831); the results were similar in both sexes." (PMID 34829886, 2021). "The results of this study showed that diabetes induction increased BW, FBG, TG, LDL-C, leptin, and TNF-α levels, and decreased insulin compared to the beginning stage." (PMID 34039404, 2021). "Herein, we also include the streptozotocin (STZ) induced diabetes model (STZ-induced DM) in which animals have little adipose tissue, insulin, or leptin." (PMID 34063911, 2021). "In summary, our study suggests that gastrectomy has an advantage over ESD in terms of better diabetes management and weight reduction in EGC patients with T2DM and that this advantage can be more prominent in those with higher leptin levels." (PMID 34501456, 2021). "As well as leptin and adiponectin, the effect of 3-n PUFA on irisin was studied in diabetes subjects: 3-n PUFA supplementation increases irisin expression." (PMID 33171610, 2020). "Studies in adults have shown a strong relationship of certain metabolic diseases, for example, diabetes, with elevated levels of CRP, TNF-α, and leptin." (PMID 33081030, 2020).
diabetes (continued). "Age, BMI, education level, duration of diabetes, history of hypertension, FBG, HbA1c, fasting leptin, plasma cortisol at 8:00 am, plasma cortisol at 4:00 pm, 24 h urinary cortisol, and FCP were not significantly correlated with depression." (PMID 33023555, 2020). "Leptin was first identified as a hunger suppressant in spontaneous hyperphagic obese (ob) mutant mice (C57BL/KsJ) with glucose intolerance and diabetes." (PMID 31661517, 2019). "Vitamin D supplementation in patients with diabetes mellitus type 2 helps decrease C-reactive protein and TNF-alpha concentrations, decrease ESR, and increase leptin concentrations." (PMID 30881343, 2019). "Her son (with the same LMNA R133L mutation) evidences no sign of fat loss and presently exhibits normal levels of leptin, adiponectin, and glucose; moreover, comparisons with other family members support the correlations among lipodystrophy, reduced adipokine levels, and diabetes in our patient." (PMID 31293201, 2019). "At the end of the study, in diabetes group, blood glucose level, GLUT2 and galanin expressions increased, while leptin expression decreased when compared to control group." (PMID 31231496, 2019). "A trio of genes encoding angiogenic factors—FGF2, CXCL12 and LEP—were downregulated by diabetes (FGF2 an CXCL12, p < 0.01 vs control group; LEP, p < 0.05 vs control group)." (PMID 31001672, 2019). "After statistical adjustment for diabetes, the statistical differences observed for the overweight group were lost; in the obese group, differences found for HDLc, PON1/HDLc, adiponectin, leptin, VLDL, large HDL, intermediate HDL, and small HDL persisted." (PMID 30911344, 2019). "The serum concentrations of leptin and adiponectin were also measured to study TGPE’s mechanisms of delaying diabetes." (PMID 29670038, 2018). "On adjustment for body mass index and diabetes, however, the PAI-1 level was comparable between group (p = 0.06), whereas leptin levels became significantly higher in the patients(p <0.001)." (PMID 28491119, 2017). "Diabetes medication status, biochemical and hormonal data including blood glucose, HbA1c, insulin, C-peptide, HOMA-IR, ghrelin, leptin, GLP-1, PYY, and GIP were evaluated for 12 months after surgery." (PMID 29216250, 2017). "Age, sex, BMI, reconstruction type, diabetes duration, preoperative blood glucose, HbA1c, insulin, C-peptide, HOMA-IR, ghrelin, leptin, GIP, PYY, and GLP-1 were analyzed." (PMID 29216250, 2017). "However, it should be noted that no animal model of diabetes fully replicates the human phenotype.ob/ob mice are deficient of the hormone leptin and it was considered that leptin itself may modulate GABAAR function (Solovyovaet al., 2009)." (PMID 28357038, 2016). "It is previously shown that leptin and CRP are correlated in healthy individuals, and we reported the lost correlation between CRP and leptin in type 2 diabetes mellitus." (PMID 27981248, 2016). "The BMI/WHtR 5-category variable was a significantly better discriminator of high triglycerides, low HDL-C, pre-diabetes, high C3, CRP, IL-6, TNF-α and WBC levels compared to BMI, and of leptin compared to WHtR." (PMID 26351521, 2015). "Few studies have investigated the levels of diabetes-related biomarkers in GCF such as ghrelin, leptin, and visfatin." (PMID 25993052, 2015). "Additionally, the BTBR ob/ob mouse model is dependent on leptin deficiency, which is not a characteristic of human diabetes.The lack of reliable animal models that closely mimic human disease has delayed the identification of specific factors that cause diabetic nephropathy." (PMID 25629817, 2015). "The association of the inflammatory related variables (adiponectin, leptin, LAR and hs-CRP) with metabolic syndrome and diabetes-related qualitative traits was evaluated in the combined group; normal and obese non-diabetic subjects." (PMID 25276234, 2014).
diabetes (continued). "Although, little evidence has shown that family history of cancer exerted an influence on the expression of leptin and its receptor directly, previous studies have indicated that the expression of leptin gene family could be modified by family history of cancer-related diseases, such as diabetes." (PMID 23593308, 2013). "Subgroup analyses examining the relation between leptin and CKD by gender, BMI categories, diabetes, and hypertension status also showed a consistent positive association." (PMID 22666590, 2012). "It has been shown that serum leptin was higher in women with SLE than in healthy controls, even after adjustment for hypertension, hyperlipidemia, and diabetes." (PMID 22584415, 2012). "Understanding the interplay between adiponectin, leptin, CRP, and IL-6 in this unique demographic may yield important insights into the pathogenesis of lean diabetes." (PMID 41523554, 2025). "When stratified by BMI, maternal leptin was higher in obese mothers with GDM compared to non-obese mothers without diabetes (p = 0.026), and non-obese mothers with T2D (0 = 0.030)." (PMID 40045330, 2025). "Pieu found that leptin mRNA expressions were significantly increased in adipose tissue of non-obese type 2 diabetes mellitus." (PMID 39877628, 2025). "Correlations between leptin and biophysical parameters in the diabetic mellitus subjects (diabetic nonobese, diabetic obese) and control." (PMID 41239622, 2025). "LTBI is known to upregulate adiponectin, leptin and FGF-21 in pre-diabetes individuals." (PMID 38327565, 2024). "Regardless of diabetes status, the obese group exhibited higher levels of leptin, lower levels of adiponectin, and higher LAR compared to the nonobese group." (PMID 39474247, 2024). "The levels of leptin and adiponectin were significantly decreased in obese groups, regardless of diabetes status." (PMID 39474247, 2024). "That leptin-peptide, leptin-1 activates IRS1 which plays crucial roles in glucose metabolism, signifies that this peptide could exert positive effects on diabetes." (PMID 39490585, 2024). "Some studies show higher levels of leptin in women, while in diabetes patients with nephropathy, no gender-based variations in leptin levels were observed." (PMID 39062887, 2024). "In the current study we observed that although leptin SR was not correlated with BFM it was significantly associated with high level of TG and uncontrolled diabetes." (PMID 36950695, 2023). "Acute COVID-19 children exhibited decreased adiponectin, and GIP and increased adipsin, leptin, C-peptide, insulin and ghrelin when compared with convalescent and control group of children without prior history of diabetes." (PMID 37013538, 2023). "It was connoted that in patients with diabetes, increased TNF-α and leptin levels might provoke the inflammatory pathways that could contribute to hepatic fibrogenesis." (PMID 35223941, 2022). "Conversely, an American prospective study reported that plasma leptin was unlikely to serve as a biomarker to predict future diabetes." (PMID 35712241, 2022). "According to our data, patients on dialysis with diabetes mellitus and patients with both diabetes mellitus and hypertension had higher leptin levels than those without diabetes mellitus or hypertension, or only with hypertension." (PMID 36289903, 2022). "In patients with malnutrition–inflammation–atherosclerosis syndrome and type 2 diabetes, compared to patients with this syndrome but without diabetes, higher levels of leptin (and IL-6 and hs-CRP) and lower HMW adiponectin values were observed." (PMID 36289903, 2022). "Biological Biochemical testing reveals hypertriglyceridemia, low HDL-cholesterol, hyperinsulinemia, glucose intolerance or diabetes, increased transaminases (hepatic steatosis), CPK can sometimes be elevated (muscle damage) and leptin (adipose tissue hormone) levels are low (leptinemia)." (PMID 35440056, 2022).